BRCA1 (BRCA1 DNA repair associated)
Diseases named in the same sentence as BRCA1 in open-access papers (continued):
Sharing a sentence is not in itself a finding about the gene and the disease.
breast cancer (continued). "Individuals carrying BRCA1 or BRCA2 mutations, associated with elevated breast cancer risk, often opt for risk-reducing mastectomies, significantly diminishing the likelihood of future breast cancer occurrences." (PMID 38674216, 2024). "After matching for age and receptor status, our findings did not suggest an earlier CNS spread in patients with BRCA1/2 mutations, and the median time from breast cancer diagnosis to CNS disease was relatively long in both groups." (PMID 38365640, 2024). "Here, we present the case of a patient with BRCA1-positive breast cancer in remission and a history of ovarian cancer with mediastinal lymphadenopathy and pulmonary nodules, with avid fluorodeoxyglucose uptake on positron emission tomography (PET) scan and elevated CA 15-3 and CA 27-29." (PMID 38586673, 2024). "Female BRCA1/2 and PALB2 germline pathogenic variant carriers have an increased lifetime risk of breast cancer and may wish to consider risk-reducing mastectomy (RRM) for surgical prevention." (PMID 38248108, 2024). "Six BRCA1/2 mutation carriers (19.4%) underwent annual breast cancer surveillance as recommended by guidelines, while none underwent ovarian or prostate cancer surveillance." (PMID 39590130, 2024). "Notably, we observed that most cases with PVs in the BRCA1 gene developed breast cancer of the triple-negative subtype, with grade III differentiation, and at a young age." (PMID 38893140, 2024). "Therefore, the testing of an extended breast cancer panel doubled the detection rate compared to BRCA1/2 testing only: 20.7% (96/463) vs. 12.1% (56/463)." (PMID 39684258, 2024). "Among the 10 breast cancer susceptibility genes, 10.3% (13/126) of patients harbored pathogenic germline variations, whereas one patient was observed to possess pathogenic variations in both RAD50 and BRCA1." (PMID 39482530, 2024). "Furthermore, YY1 binds to the BRCA1 promoter and increases its expression of BRCA1 and other downstream genes in breast cancer." (PMID 39796650, 2024). "Two human breast cancer genes, BRCA1 and BRCA2, and the CDK5RAP2 gene involved in the cell cycle regulation, have been linked with increased odds of mammary tumours in the English Springer Spaniel, a breed at high risk of mammary tumours which is closely related to the ECS." (PMID 38233914, 2024). "Tumors with an impaired ability to repair DNA double-strand breaks by homologous recombination, including those with alterations in breast cancer 1 and 2 (BRCA1 and BRCA2) genes, are very sensitive to blocking DNA single-strand repair by inhibition of the poly (ADP-ribose) polymerase (PARP) enzyme." (PMID 39351435, 2024). "Moving beyond BRCA1 and BRCA2, rare germline pathogenic variants (PVs) in other genes that have a role in the DNA repair pathway of homologous recombination also confer risks for breast cancer." (PMID 39001430, 2024). "Following the survival benefit demonstrated in the OlympiA trial, one year of adjuvant olaparib is now recommended for all patients with germline BRCA1/2 pathogenic/likely pathogenic variants (PV) and high-risk, HER2-negative early breast cancer after chemotherapy." (PMID 38627457, 2024). "Tumor suppressor genes BRCA1, BRCA2, PALB2, and RAD51C play crucial roles in homology-directed recombination DNA repair (HDR) activity, and mutations in these genes have been implicated in breast cancer." (PMID 39430403, 2024). "Delaying surgical menopause for at least 5 years could have a significant impact on quality of life and long term health, especially in BRCA1 PV carriers with a personal history of breast cancer." (PMID 39624976, 2024). "A hypothetical BRCA‐3 gene has been suggested for families with a significant history of breast cancer but no identified mutations in BRCA‐1 or BRCA‐2." (PMID 38827026, 2024). "There are only a few studies that have investigated the risk of breast cancer by HRT in non-diseased BRCA1/2-pV carriers after RRSO." (PMID 39259360, 2024).
breast cancer (continued). "Pathogenicity of BRCA1:c.5017_5019del(p.His1673del) has been confirmed; however, breast cancer risk in Italian families is not increased, unlike in families from other countries and in carriers of most BRCA1 pathogenic variants." (PMID 39194334, 2024). "BRCA1 mutations appear in 50–80% and BRCA2 mutations in 40–70% of breast cancer risks." (PMID 38791944, 2024). "This study, thus, suggests that inhibiting inflammasome activation could be a potential therapeutic strategy to control tumor recurrence and metastasis in BRCA1-related breast cancer." (PMID 39769450, 2024). "Of 491 breast cancer patients with P/LP variants in breast cancer susceptibility genes, 72.3% (n = 355) were BRCA1 or BRCA2 variants, while 139 patients had non-BRCA variants." (PMID 38355628, 2024). "Moreover, previous studies have demonstrated that the overexpression of BRCA1 in breast cancer cells that lack BRCA1 gene significantly upregulates FADD expression." (PMID 38542202, 2024). "Common breast cancer biomarkers include proteins such as HER2 (Human Epidermal Growth Factor Receptor 2), CA15-3 (Cancer Antigen 15-3), and CEA (Carcinoembryonic Antigen), as well as genetic markers like BRCA1 and BRCA2 mutations and specific microRNAs." (PMID 39275589, 2024). "Moreover, they found that an increased Fgfr2 resulted in a lower Brca1, promoting tumorigenesis in basal-like mammary tumours." (PMID 39596875, 2024). "A study was conducted on 63 Finnish breast cancer patients without any BRCA1/2 variants who had an onset of breast cancer at age 40 or younger." (PMID 39272813, 2024). "The Gail model asks a series of questions, which include a medical history of breast cancer, a mutation in the BRCA1 or BRCA2 gene, age, age at first menstrual period, age at first live birth, first-degree relatives with breast cancer, breast biopsy, and race/ethnicity." (PMID 38501027, 2024). "According to a Korean BRCA1/2 negative breast cancer cohort study, it was confirmed that 2.43% (17/700) of BRCA1/2 negative breast cancers were caused by PALB2 variants." (PMID 39409938, 2024). "However, when incorporating the bulk RNA-seq dataset GSE202203 with an additional 3,207 breast cancer samples, the distribution fitting reveals that BRCA1 still follows a log-normal distribution, while BRCA2 shifts to a genextreme distribution." (PMID 39541191, 2024). "Initial studies that examined the effect of a PRS on breast cancer risk in BRCA1 and BRCA2 carriers showed the absolute lifetime risk of breast cancer was around 10%–20% greater for carriers in the highest decile of the PRS distribution compared with the lowest." (PMID 39107016, 2024). "Enhanced screening of BRCA1 carriers with MRI surveillance leads to early detection of breast cancer but does not reduce the risk." (PMID 38892720, 2024). "The interplay between hormonal dynamics, particularly elevated progesterone levels in BRCA1 mutation carriers, the RANK/RANKL signaling pathway, and ELF5 may provide a crucial mechanistic link to the increased breast cancer risk observed in these individuals." (PMID 38275872, 2024). "Additionally, there is a 63% risk of developing a second primary contralateral breast cancer within 25 years of the initial diagnosis for carriers affected with BRCA variants, with BRCA1 carriers having the highest risk." (PMID 38792636, 2024). "Consistently, Western blot analysis of USP4 and BRCA1 in multiple breast cancer cell lines including luminal and triple negative breast cancers, and normal human mammary epithelial cells further implied that expression of USP4 and BRCA1 is positively correlated." (PMID 38734703, 2024). "The BRCA1/2 genes are the most significant tumor suppressor genes involved in breast cancer." (PMID 38773604, 2024).
breast cancer (continued). "While the retrospective studies have suggested that the cancer risk might vary between BRCA1 and BRCA2 mutation carriers, recent prospective studies have shown that the lifetime breast cancer risk is similar for both genes ranging from 55 to 72%." (PMID 38254240, 2024). "Metcalfe et al25 reported a 10-year risk of contralateral breast cancer of 43.4% for BRCA1 carriers and 34.6% for BRCA2 carriers who did not undergo oophorectomy or take tamoxifen." (PMID 38916888, 2024). "LncRNAs act through direct functional interactions with specific proteins, forming lncRNA ribonucleoprotein complexes (lncRNPs), such as the complex that allows the BRCA1 protein in breast cancer to function upon activation by a direct-binder primate-specific lncRNA." (PMID 39346726, 2024). "Indeed, although their combined frequency exceeds BRCA1/2 they were only included officially on NHS England breast cancer gene panels in 2021." (PMID 38478259, 2024). "In a meta-analysis that included 13,965 BRCA1 and 7,057 BRCA2 mutation carriers enrolled on 14 observational studies, the breast cancer risk among BRCA1 mutation carriers was lowered by RRSO (HR = 0.63, 95% CI, 0.49-0.81, P < 0.01) and BRCA2 mutation carriers (HR= 0.51, 95% CI, 0.34-0.75, P < 0.01)." (PMID 39507757, 2024). "Comparison of Brca1 tumour cohorts showed little difference in mammary tumour formation between animals that were wild type, heterozygous or homozygous for the conditional Lyn allele, although this was confounded by factors including incomplete Lyn recombination in some tumours." (PMID 38149669, 2024). "Additionally, mutations in DNAH11 have been reported in BRCA1‐ and BRCA2‐negative breast cancer families, further supporting its role in cancer predisposition." (PMID 38970307, 2024). "The cellular response to cisplatin has also been assessed in an in vivo model of xenografts of BRCA1-methylated and unmethylated breast cancer cells, which showed that xenografts of BRCA1-methylated cells were significantly smaller following cisplatin treatment than xenografts of unmethylated cells." (PMID 38256203, 2024). "Genetic alteration in HRR genes may confer increased risk of multiple genetically-related malignancies, such as ovarian cancer, breast cancer, pancreatic cancers, especially BRCA1 and BRCA24,5." (PMID 38509102, 2024). "Hereditary breast cancer, also known as familial breast cancer (FBC), accounts for 15% of all breast cancer cases, with HBOC syndrome, which is associated with BRCA1 or BRCA2 mutations and significantly increases the risk of breast and ovarian cancer, especially before the age of 50." (PMID 38543119, 2024). "Three breast cancer samples showed BRCA1 promoter hypermethylation." (PMID 39406235, 2024). "TNBC was the most frequent breast cancer immunophenotype in BRCA1 carriers (75.6%)." (PMID 39001430, 2024). "BPA can alter the environment surrounding a tumour, which is critical for cancer growth, and can induce hypermethylation, an epigenetic process that increases the risk of breast cancer; for example, BPA can cause hypermethylation of BRCA1 in human mammary epithelial cells." (PMID 39846533, 2024). "First, given the absence of a population-based registry of breast cancer survivors carrying a BRCA1/2 mutation, a convenience sample was used." (PMID 39192282, 2024). "BRCA1/2 mutation carriers exhibited a higher rate of bilateral breast cancer compared to non-carriers, which is consistent with previous reports." (PMID 38167124, 2024). "BRCA1 and BRCA2 pathogenic variant carriers develop breast cancers with distinct pathological characteristics and mutational signatures that may result in differential response to chemotherapy." (PMID 39060255, 2024).
breast cancer (continued). "Indeed, some of the DDR genes implicated in these experimental studies (e.g., TP53BP1 and MRE11A) have also been observed in PARPi-resistant tumors from patients with BRCA1/2-mutant breast cancer." (PMID 38956205, 2024). "Furthermore, studies have shown that the BRCA1 mutation stimulates inflammasome activation and IL-1β secretion via ROS production and cGAS-STING activation, thereby promoting breast cancer metastasis." (PMID 38473997, 2024). "Meta-analysis studies show a negative impact of the BRCA1 mutation on overall survival, especially in certain populations, such as Ashkenazi Jewish breast cancer patients." (PMID 38543119, 2024). "Approximately 5-10% of men with BRCA2 develop breast cancer, compared to 1-2% with BRCA1." (PMID 39314558, 2024). "Does hormone replacement therapy (HRT) after risk-reducing salpingo-oophorectomy (RRSO) influence breast cancer risk of non-diseased BRCA1/2-pV carriers or carriers of pV in genes of Lynch syndrome?" (PMID 39259360, 2024). "BRCA1/2 mutation carriers had a higher rate of bilateral breast cancer (9/72, 12.5%) compared to non-carriers (11/337, 3.3%)." (PMID 38167124, 2024). "In the breast cancer subgroup, variants in BRCA2 and BRCA1 were the most frequently detected." (PMID 39148954, 2024). "While BRCA1 and BRCA2 remain the most well-known high-penetrance genes, others, such as ATM, BARD1, CHEK2, PALB2, RAD51C, and RAD51D, are now recognized as conferring moderate to high risk for breast cancer." (PMID 39590369, 2024). "The tgRNA-programmed Cas12b-mediated DNA detection (CDetection) could detect the human BRCA1 gene with a SNP (3232A > G) responsible for breast cancer." (PMID 39189452, 2024). "A more recent retrospective cohort study by Michaelson-Cohen investigated the risk of breast cancer after RRSO in 306 non-diseased BRCA1/2-pV carriers." (PMID 39259360, 2024). "In addition, mutations in genes such as BRCA1 and BRCA2 can significantly increase the risk of developing breast cancer." (PMID 39795956, 2024). "Furthermore, mutations in BRCA1 and BRCA2 are more commonly associated with HER2-positive breast cancer." (PMID 38256428, 2024). "We may thus have a smaller fraction of individuals at the end-tail of the PRS distribution (PRS >99th percentile tested in this study) with an odds ratio equivalent to BRCA1 (OR = 10.57) and BRCA2 (OR = 5.85) mutations in the field of breast cancer." (PMID 38970920, 2024). "BRCA1 plays a pivotal role in the suppression of human breast cancer." (PMID 38734703, 2024). "BRCA1 plays critical role in the suppression of breast cancer." (PMID 38734703, 2024). "Ovarian hyperstimulation with clomiphene or gonadotropins probably does not increase breast cancer risk in BRCA1/2-pV carriers or pV-carriers in other risk genes for breast and ovarian cancer." (PMID 39259360, 2024). "Q2: Women with breast cancer and a strong family history should perform BRCA1/BRCA2 testing." (PMID 39446329, 2024). "Additionally, BRCA1 PVs contribute to breast cancer development through epigenetic effects on cells, including DNA methylation and histone acetylation, leading to the suppression of proto-oncogenes and dysregulation of cytokines." (PMID 39682099, 2024). "Patients with BRCA1 mutations in breast cancer benefit more from platinum-based protocols than patients with BRCA2 mutations, suggesting that patients with BRCA1 mutations may be more sensitive to platinum-based drug therapy." (PMID 40231011, 2024). "Additionally, emerging evidence suggests a potential link between autophagy, DNA damage, and caretaker breast cancer genes BRCA1/2, highlighting the interplay between DNA repair mechanisms and cellular homeostasis." (PMID 39199310, 2024).
breast cancer (continued). "Of 37 patients with BRCA1 variants who underwent bilateral mastectomy, 14 (37.8%) did so in the absence of an ipsilateral or contralateral breast cancer event." (PMID 38916888, 2024). "The control group consisted of 62 age-matched women with no prior history of cancer, selected for high-risk breast cancer surveillance due to BRCA1 or BRCA2 mutations." (PMID 39682278, 2024). "Even though many are not yet diagnosed with breast cancer, approximately 46% of BRCA1 mutation carriers and 52% of BRCA2 mutation carriers are diagnosed with breast cancer at some point in their lifetime." (PMID 38791944, 2024). "Moreover, PI3K activation caused the BRCA1 overexpression and re-sensitized cells to CDDP treatment in breast cancer." (PMID 38184597, 2024). "Results of this cohort study suggest that among women with a BRCA1 sequence variation, MRI surveillance was associated with a significant reduction in breast cancer mortality compared with no MRI surveillance." (PMID 38421676, 2024). "In summary, the prevalence of germline pathogenic PALB2 variants was approximately 0.77% in Chinese patients with BRCA1/2-negative early-onset breast cancer patients, irrespective of family history." (PMID 38914840, 2024). "Moreover, the genetic landscape of OC is explored through the examination of mutations in genes such as BRCA1 and BRCA2 (Breast Cancer genes 1 and 2)." (PMID 38535506, 2024). "For individuals carrying BRCA1 or BRCA2 mutations and diagnosed with HER2- breast cancer, treatment with PARP inhibitors such as olaparib and talazoparib may be considered." (PMID 38167124, 2024). "While the genetic basis of BRCA1/2 hereditary breast cancer is well-studied, the role of epigenetic mediators in the tumourigenesis of these hereditary breast cancers is also worth exploring because the expression and suppression of these genes do have a component of epigenetic regulation." (PMID 39682099, 2024). "Among the genes known to play a relevant role in mammary tumors, BRCA1 (BReast CAncer gene 1) and PALB2 (Partner And Localizer of BRCA2), two breast cancer susceptibility genes whose mutations result in familial cases of the disease, seem to be required for RARα signaling." (PMID 38360674, 2024). "Using the Breast CFR, we found strong evidence that OC use was associated with a substantial (4.5‐fold; p = 0.0001) protective association against breast cancer diagnosed before age 40 for BRCA1 carriers, but not for BRCA2 carriers or noncarriers." (PMID 38504141, 2024). "Numerous studies have identified BRCA1 and BRCA2 (BRCA1/2) as important components of homologous recombination (HR), a specific DNA repair mechanism, in which mutations in these genes frequently lead to HRD in breast cancers." (PMID 38745917, 2024). "Genetic testing could be offered to women with a familial history of breast cancer due to the identification of the BRCA1 and BRCA2 genes, mutations which may be associated with the development of breast cancer." (PMID 38473036, 2024). "Later studies revealed BECN1 is adjacent to breast cancer 1 (BRCA1) on chromosome 17q21, and BECN1 deletion does not occur independently of BRCA1, indicating BRCA1 loss is the primary mutation responsible for breast cancer development." (PMID 38741166, 2024). "BRCA1, a highly penetrant gene, plays a crucial role in breast cancer oncogenesis." (PMID 38952531, 2024). "As the BRCA1 familial variant was not sufficient to explain both pancreatic cancers, those in the patient and his sister, as well as their mother’s breast cancer, we re-initiated a CPG analysis and this showed that he carried two pathogenic variants: the known familial BRCA1 PV, and a BRCA2 PV." (PMID 38929805, 2024). "Mutations in BRCA1 and BRCA2 are observed in approximately 25% of breast cancer cases." (PMID 38927753, 2024). "Germline BRCA1/2 mutations (gBRCA1/2 m) are the most common and could contribute to over 20% of the HRD features in breast cancer patients." (PMID 39334297, 2024).